COL4A2 (collagen type IV alpha 2 chain)
Diseases named in the same sentence as COL4A2 in open-access papers (continued):
Sharing a sentence is not in itself a finding about the gene and the disease.
cancer (continued). "The extended analysis of top seven collagen genes among 11 cancer types shows a consistent positive correlation between the fractions of endothelial cells and expression of basement membrane (COL4A1 and COL4A2) and multiplexin (COL15A1) collagen subfamily." (PMID 36321857, 2022). "Collagen type IV alpha 2 (COL4A2), a major component of the basement membrane, dynamically influences a wide range of biological processes, including cancer pathogenesis and progression." (PMID 27906681, 2017). "In this scenario, the vast majority of CpG island promoter methylated genes represent passenger events with only a few true cancer driving events found in each case; in this context, DZIP1, COL4A2, L3MBTL4, IRX1 and RASSF10 are named as likely candidates." (PMID 25468711, 2015). "No up-regulated genes, but four down-regulated genes (COL4A1, COL4A2, EPAS1 and FGF15) of the "Pathways in cancer" were found in both cell lines." (PMID 25992885, 2015). "The biological relevance of the aberrantly methylated and expressed genes was cancer process, including IRS1 that is related to transformation, and collagen-related genes such as COL4A1, COL4A2 and COL6A3." (PMID 23818951, 2013). "The results indicated that COL4A2 was mainly involved in cell adhesion molecules, chemokine signaling pathway, ECM- receptor interaction, local adhesion, leishmania infection, and pathways in cancer." (PMID 37266443, 2023). "Besides VIM, the basement membrane also promotes cancer cell invasion and metastasis, COL4A1 and COL4A2 are typical basement membranes ubiquitously expressed on cells." (PMID 37642765, 2023). "For example, we identified the driver gene set including ATR, COL4A2, and FLT1 in GBM individual TCGA‐12‐0821, and the Dscores of dysfunctional cancer hallmarks showed significant correlation with Escores of these cancer hallmarks (PCC = 0.86 and P = 1.25e‐08)." (PMID 37491836, 2023). "Based on our findings, we have concluded that combinatorial treatment by CXCR4-ligand modified L1-polyplexes formed with AQP3, CDC20, and COL4A2 siRNAs effectively inhibits proliferation of TNBC cells and can be suggested as useful tool for RNAi-mediated cancer therapy." (PMID 34681181, 2021). "In addition, six of the frequently hypermethylated genes, i.e., CCND1, COL4A2, HDAC2, AXIN2, ABL1 and GLI2, are included in the pathways in cancer map from the KEGG database." (PMID 22159500, 2012). "At the same time, multiple collagen-related genes (COL6A2, COL3A1, COL4A1, and COL4A2) in the MSC-2 cluster were upregulated in bone metastases, which is consistent with our observation of IGFBP3, TAGLN, LUM, COL6A1, COL6A2, and COL3A1 in pan-cancer in Fig. (1d)." (PMID 39156727, 2024). "Interestingly, recent studies show that cleavage products derived from the non-collagenous domain of both COL4A1 and COL4A2, have significant anti-angiogenic effects on endothelial cells including increased apoptosis and decreased proliferation, and are being explored as novel cancer therapeutics." (PMID 26010865, 2015).
kidney disease (3 papers, 2014 to 2024). "COL4A2 is the obligatory protein partner of COL4A1 but in contrast to most COL4A1 mutations, the COL4A2 mutation does not lead to eye or kidney disease." (PMID 24001601, 2014).
cardiac diseases (2 papers, 2021 to 2022). "Several reports have shown that mutations in Col4a2 and Col4a1 are linked to heart diseases." (PMID 34648499, 2021). "Those proteins can directly or indirectly interact with overrepresented pathway-related genes in fibroblasts, like Ywhap, Prkcd, Col4a2, and Cbl, which provides the direction for further research on the role of intercellular communication in cardiac diseases." (PMID 35252172, 2022).
muscular disorders (1 paper, 2018). "We additionally identified two different damaging missense variants in COL4A2, which is involved in muscular disorders (OMIM 120090), inherited from the mother of case G and from the father of case Q." (PMID 28771244, 2018).
retinopathy (1 paper, 2021). "In the retina, Col4a1 and Col4a2 are mainly present in basement membranes of the choriocapillaries vasculature and Col4a1 mutation causes highly penetrant and progressive retinopathy that is secondary to vascular defects." (PMID 33918807, 2021).
COL4A2 also shares sentences with these, for which no sentence is quoted: myopathy (7 papers); neurological diseases (4); preeclampsia (4); cardiovascular disease (3); fibrosis (3); colorectal cancer (2); developmental delay (2); glioblastoma (2); Hydrocephalus (2); keratoconus (2); melanoma (2); polymicrogyria (2); schizophrenia (2); viral infection (2); adenoma (1); Alzheimer disease (1); amblyopia (1); ameloblastoma (1); apraxia (1); asthma (1); basal cell carcinoma (1); carotid atherosclerosis (1); central nervous system disorder (1); Cerebellar atrophy (1); cerebral autosomal recessive arteriopathy with subcortical infarcts and leukoencephalopathy (1); cerebral microbleeds (1); clear cell renal cell carcinoma (1); complication (1); connective tissue disorder (1); coronary artery (1).
A further 58 diseases each share a sentence with COL4A2 in 1 paper.